ENSG00000197550 (zinc finger pseudogene)
Gene: Unprocessed pseudogene on chromosome 9 (64,817,870 to 64,836,341, forward strand). Ensembl gene ENSG00000197550.
Diseases named in the same sentence as ENSG00000197550 in open-access papers:
ENSG00000197550 is named in the same sentence as 1 disease in open-access papers, as found by Europe PMC text mining. Sharing a sentence is not in itself a finding about the gene and the disease.
ENSG00000197550 shares sentences with these, for which no sentence is quoted: myopia (1 paper).